ZNF697 (zinc finger protein 697)
Description:
RNA-interacting protein with a high number of miRNA targets. Acts as a damage-induced regulator of muscle remodeling by mediating the interferon gamma response in muscle cells.
Synonyms: MGC45731; ZFP697
Tractability: PROTAC: UniProt records ubiquitination sites on it.
Gene: Protein-coding gene on chromosome 1 (119,619,377 to 119,648,454, reverse strand). Ensembl gene ENSG00000143067.
Subcellular location: Nucleus
Subcellular location (Human Protein Atlas): Nucleoplasm
Pathways (Reactome):
Gene expression (Transcription): Generic Transcription Pathway
Gene Ontology:
Molecular function: protein binding; DNA-binding transcription factor activity, RNA polymerase II-specific; miRNA binding; RNA polymerase II cis-regulatory region sequence-specific DNA binding; nucleic acid binding
Biological process: regulation of transcription by RNA polymerase II; response to type II interferon
Cellular component: nucleus
Genetic constraint (gnomAD): Loss-of-function variants: 23 observed, 18.82 expected, observed/expected ratio (o/e) 1.22, 90% interval 0.88 to 1.71. The synonymous counts are far from expectation, so gnomAD's model fits this gene poorly and the ratio says little. Missense variants: 927 observed, 661.64 expected, observed/expected ratio (o/e) 1.4, 90% interval 1.33 to 1.48. Synonymous variants: 417 observed, 272.86 expected, observed/expected ratio (o/e) 1.53, 90% interval 1.41 to 1.66.
Homologues: Orthologues: chimpanzee ZNF697 (99% identical), macaque ZNF697 (97% identical), pig ZNF697 (92% identical), mouse Zfp697 (90% identical), rat Zfp697 (90% identical), dog ZNF697 (88% identical), guinea pig ZNF697 (88% identical), rabbit ZNF697 (88% identical). Paralogues in human: ZNF287 (36% identical), ZNF17 (35% identical), ZNF34 (34% identical), ZNF572 (33% identical), ZNF527 (33% identical), ZNF214 (32% identical), ZNF416 (32% identical), ZNF530 (32% identical), ZNF774 (32% identical), ZKSCAN7 (32% identical), ZNF233 (30% identical), ZNF467 (30% identical), and 38 more.
Diseases named in the same sentence as ZNF697 in open-access papers:
ZNF697 is named in the same sentence as 2 diseases in open-access papers, as found by Europe PMC text mining. Sharing a sentence is not in itself a finding about the gene and the disease. The quoted sentences say what the papers report.
colon cancer (1 paper, 2025). "In conclusion, we have developed a gene expression score, based on ZNF697, CTSC, SNORA2B, and OXLD1, that effectively stratifies patients with stage II colon cancer into low and high‐risk groups, facilitating the identification of patients who may benefit from adjuvant chemotherapy." (PMID 40478186, 2025). "A dichotomized score, derived from the combined expression of four RNAs (ZNF697, SNORA2B, CTSC and OXLD1), effectively predicted TTR in stage II colon cancer patients." (PMID 40478186, 2025).
cancer (2 papers, 2024 to 2025). A tumor composed of atypical neoplastic, often pleomorphic cells that invade other tissues. "Future research should explore the roles of ZNF697, NPAS2, and genomic reorganization in polyploid cancer cells and their implications for disease recurrence in progeny cells." (PMID 39578659, 2025). "Future research should explore the roles of ZNF697 and NPAS2 in polyploid cancer cells and their implications for disease recurrence in progeny cells." (PMID 39483900, 2024).